EGFR (epidermal growth factor receptor)
Diseases named in the same sentence as EGFR in open-access papers (continued):
Sharing a sentence is not in itself a finding about the gene and the disease.
tumor (continued). "When HER2 and EGFR are overexpressed in patients with NSCLC, they exhibit aggressive tumor cell growth and enhanced sensitivity to EGFR tyrosine kinase inhibitors (TKIs)." (PMID 33578653, 2021). "For example, AR mechanisms were explored using circulating tumor DNA analysis in patients who were enrolled in the phase-III FLAURA study, which compared the efficacy of first-line osimertinib to first-generation EGFR-TKIs (gefitinib or erlotinib)." (PMID 33572269, 2021). "In WT EGFR NSCLC, gefitinib and erlotinib treatment lead to a decrease in VEGF concentrations in tumour cells." (PMID 34298636, 2021). "The third method is tumor genomic biomarkers, such as MDM2/MDM4 amplifications and EGFR alterations." (PMID 34733781, 2021). "With the wide application of targeted drugs such as EGFR-TKIs and ALK-TKIs, NSCLC has become the most developed tumor type of precision medicine field." (PMID 34336662, 2021). "In fact, exposure of either normal or tumor epithelial cells to IL-1, TNFα, or IFNγ upregulates the expression of the EGF receptor (EGFR)." (PMID 34948338, 2021). "Integrative analysis of multiomics data identified EGFR, JUN, MYC, FN1 and SERPINE1 as key modulators of the tumour immune microenvironment and potential targets for combination therapies which was validated in two validation sets." (PMID 33971902, 2021). "In this open-label, multi-center study, larotinib demonstrated promising anti-tumor activity and manageable toxicity profiles in previously treated patients with advanced and metastatic ESCC with EGFR overexpression or amplification." (PMID 34688250, 2021). "Among MMRp CRCs, we found MYC and FLT3 amplification in one tumor (T32), MYC and CCND1 amplification in 1 tumor (T36), and EGFR amplification in one tumor (T38)." (PMID 33435234, 2021). "RT-PCR analysis of CXCR4, FGF-2, VEGF-A, EGFR, and ERK2 (MAPK1) revealed significantly higher expression of three genes (i.e., CXCR4, FGF-2, and ERK2) in IR/Ipsi-tumor and IR/Contra-tumor groups compared to the control groups." (PMID 34764346, 2021). "In fact, miR-7 showed high efficacy in blocking directly the EGFR pathways and downregulate MAPK/PI3K/Akt signaling, resulting in tumor cell apoptosis." (PMID 34439595, 2021). "In addition, a recent 3rd-generation EGFR-TKI, osimertinib, had a statistically significant and clinically meaningful improvement in disease-free survival in patients with common sensitive EGFR-mutated NSCLC after complete tumor resection and adjuvant chemotherapy." (PMID 34217313, 2021). "The in vitro and in vivo evaluations of the EGFR mAb-Lipo-drugs (i.e., GC/DM1) showed high TNBC targeting and anti-tumor efficacy in cell lines and PDX xenograft mouse models." (PMID 34359650, 2021). "Next, we analyzed the expression level of pHER2, HER2, pEGFR, EGFR, Ki-67, cleaved PARP (cPARP), and Bim in tumor tissue samples by immunohistochemistry (IHC) staining." (PMID 34203351, 2021). "For these reasons, the KRAS status of liquid biopsy tends to be less reflective in NRAS, BRAF, EGFR, and MSI of the origin tumor." (PMID 34442609, 2021). "This study used an EGFR-overexpressed PDX line to mimics the heterogeneity and tumor microenvironment of TNBC." (PMID 34359650, 2021). "In response to acquired EGFR TKI resistance, recurrent tumor tissues from 6 of 9 patients demonstrated upregulated SGLT1 expression." (PMID 34155348, 2021). "BiKEs and TriKEs targeting tumor antigens HER2, EGFR, EpCAM, B7H3 and CD133 exhibit powerful therapeutic effects against corresponding solid tumors by boosting NK immune responses in preclinical studies." (PMID 35008589, 2021). "Western blotting was used to detect the effects of LR004-VC-MMAE on EGFR, ERK, MEK phosphorylation and tumor stemness marker gene expression." (PMID 34879870, 2021).
tumor (continued). "Thus, our model predicts that administering EGFR-targeted drugs soon after tumor removal surgery can instead stimulate cancer cells to proliferate and to form new colonies in cooperation with internal molecules of EGF, which level may be increased following surgery." (PMID 33748471, 2021). "AC-480 inhibits heterodimerization of EGFR and HER2 receptors, this adds an alternative tumor-inhibiting mechanism in which receptor co-expression and heterodimerization contribute to tumor development." (PMID 34885957, 2021). "And recently, they also found blocking EGFR palmitoylation inhibited activation of the kinase PI3K and reduced tumor growth in KRAS-mutant lung cancer." (PMID 34803494, 2021). "Interestingly, when reformatted as bispecific together with EGFR-specific binder 60F06 killing capacities were more pronounced than for 60H05 SEEDbodies, clearly indicating dependencies of cytotoxic synapse formation on the tumor targeting antigen binding site of the bispecific molecule." (PMID 35087526, 2021). "Next, we tried to use patient-derived EGFR TKI-resistant NCI-H820 cancer cells for the tumor xenograft assay, but we were unable to detect tumor growth even 3 months after mouse inoculation." (PMID 34203709, 2021). "The results were validated by IHC analysis, suggesting that Gi/o-GPCRs likely regulate EGFR and HER2 activation in tumor cells." (PMID 34343132, 2021). "EGFR mutations are good predictive markers of efficacy of EGFR tyrosine kinase inhibitors (EGFR‐TKI), but whether comprehensive genomic analysis beyond EGFR itself with circulating tumor DNA (ctDNA) adds further predictive or prognostic value has not been clarified." (PMID 33982444, 2021). "However, the role of tumor-derived exosomal circRNA on EGFR-TKIs resistance remains unclear." (PMID 33952725, 2021). "Cisplatin further enhanced the positive correlation between the area of tumor colonies and gene expression of PGE2S, EGFR, FOLR1, EP3, COX2, and VEGFA in cancer cells, highlighting the importance of these genes in treatment resistance." (PMID 33671869, 2021). "Significant increases were observed in the expressions of CXCR4, FGF-2, VEGF-A, EGFR and ERK2 (MAPK1) in the IR/Ipsi-tumor group compared to the Sham-IR/Tumor group." (PMID 34764346, 2021). "Our study demonstrated that the anti‐tumour action induced by blue LED irradiation was mediated by both ROS and EGFR/Beclin‐1‐mediated autophagy signalling pathway in human OS." (PMID 33960631, 2021). "Core fucosylated EGFR, TGFBR, E-cadherin, PD1/PD-L1 and α3β1 integrin are potential targets for tumour therapy." (PMID 34093814, 2021). "Small biopsies and cytology specimens still are the mainstay of tissue procurement during EGFR TKI therapy, which limits the potential broad applicability of large panel strategies, for which larger amounts of tumor material are necessary." (PMID 34849493, 2021). "The bi‐EGF‐IT has an increased binding affinity in vitro and is more effective and less toxic at inhibiting primary HNSCC tumor growth and metastasis in vivo compared with mono‐EGF‐IT, representing a promising EGFR‐targeted drug candidate for HNSCC treatment." (PMID 33540470, 2021). "For example, we found indices of faster cell reproduction and tumor growth in MGMT-methylated and EGFR-amplified tumors." (PMID 34298788, 2021). "EGFR can inhibit autophagy by targeting negative regulators of autophagy, such as PI3K, AKT, and mTOR, contributing to chemoresistance and tumor progression." (PMID 34830108, 2021). "These nodes include the machinery for ACh production in the tumor microenvironment, selective inhibitors of M3R activation and MMPs, like MMP7 which mediates release of HB-EGF and activation of EGFR, and a host of key downstream signaling molecules." (PMID 33450835, 2021). "Treatment of tumors with EGFR targeted photosensitizer, prior to daunorubicin treatment led to super-enhanced permeability and retention (SUPR), enhanced tumor accumulation, and therapeutic efficacy." (PMID 34207137, 2021).
tumor (continued). "Some tumor biomarkers varied as the cell cycle progressed, such as CA9, TK1 and EGFR, which were more abundantly expressed at early S stage." (PMID 34691667, 2021). "Currently, alterations in EGFR and ALK genes are considered important predictive biomarkers in NSCLC, since their identification in the tumor genome can determine a better outcome if a targeted therapy is implemented." (PMID 33916986, 2021). "The loss of oncogenic RAS and SMAD4 signals synergistically upregulate the abnormal expression of EGFR and ERBB2, leading to the development of neoplasm and the metastasis and spread of the primary tumor." (PMID 34301194, 2021). "DMG tumours regularly display focal amplifications in PDGFRA and EGFR accompanied by amplifications in KIT, KDR, EGFR and MET." (PMID 34944870, 2021). "As shown in the clinical relevance part of this study, TCGA analysis revealed that EGFR and PLK1 expression was relatively higher in the tumor tissues of LUAD patients compared with normal tissues." (PMID 34503223, 2021). "The tumor-related plasma markers YKL-40 and the extracellular domain of EGFR and osteopontin were inversely correlated with overall survival." (PMID 34210107, 2021). "Therefore, anti-EGFR may potentially be considered in patients with right-sided CMS4 tumours." (PMID 34253874, 2021). "However, we could not find any such correlations between EGFR expression and FoxP3 mRNA expression in tumours expressing either wt or mutated forms of the EGFR." (PMID 35052732, 2021). "Increased levels of EREG activate EGFR downstream pathways and synergistically enhance IL-6/STAT3 signaling in malignant tumor progression." (PMID 34884633, 2021). "Besides, ARID1A alterations or expression loss could contribute to the resistance to EGFR-TKIs via a variety of pathological process during tumor development, including epithelial to mesenchymal transition (EMT), angiogenesis of tumor and the inhibition of apoptosis." (PMID 34715776, 2021). "Taken together, the data indicated that well-differentiated tumor cells expressed MICA/B, EGFR, and PDL1 and that the treatment of these tumors with their respective antibodies mediated ADCC by the NK cells." (PMID 33440654, 2021). "AXL dimerizes with and phosphorylates EGFR to promote activation of the PLCγ-PKC-mTOR signaling cascade and tumor cell survival." (PMID 34830794, 2021). "After EGFR inhibition, TET1 binds to the promotor of the tumour suppressor genes and induces its repression through DNA demethylation." (PMID 34656178, 2021). "A heatmap analysis revealed that EGFR and PLK1 expression was relatively higher in tumor tissues than those in normal tissues." (PMID 34503223, 2021). "Other mechanisms of action include enzymatic degradation of the extracellular matrix and tumor cell attachments, alteration of signaling through modification of the surface ligands and receptors (such as Notch, HER2, EGFR, and NKG2D)." (PMID 34830179, 2021). "Among ten patients whose tumours stained high for EGFR and MET expression, 90% had a tumour response." (PMID 34898564, 2021). "Recently, it has been shown that N-cadherin allows the metastatic behavior of tumor cells by directly mediating cell-cell adhesion, and through its involvement in modulating critical signaling pathways such as TGF-β1, Wnt/β-catenin, EGFR, and NF-κB." (PMID 34948155, 2021). "The findings in vivo further indicated that CDR1as acted as an oncogene, up-regulating the proliferation index Ki-67, EGFR, CCNE1, and PIK3CD levels, thus inhibiting the anti-tumor effects of tumor suppressor miR-7." (PMID 34830377, 2021). "In another study, SLM was targeted to bulk tumor cells and CSC in osteosarcoma tumor model by encapsulation in LP NPs conjugated with anti-CD133 and anti-EGFR aptamers." (PMID 34361141, 2021). "The activation of the TLR4 signaling pathway in tumor cells by LPS can induce tumor proliferation through the COX-2 and EGFR pathways, and can promote metastasis via the NADPH oxidase 1-dependent ROS pathway." (PMID 33628591, 2021).
tumor (continued). "When evaluated on patient-derived xenograft models of EGFR mutant NSCLC, the AURKA inhibitor plus rociletinib or osimertinib was significantly better at inhibiting tumor growth." (PMID 34944063, 2021). "Epidermal growth factor receptor (EGFR) modulates CRC initiation and progression due to its key role in activating downstream signaling pathways that control tumor cell growth, differentiation, and proliferation." (PMID 34066710, 2021). "Here we displayed that ASP4132 treatment similarly induced PDGFRα-EGFR protein degradation and inhibited downstream Akt activation in NSCLC cells and xenograft tumor tissues." (PMID 33824293, 2021). "The tumor cell-derived CCL2 transforms monocytes into M2-like macrophages, resulting in the increased production of EGF, which activates EGFR signaling in the tumor cells promoting the formation of invadopodia associated with increased HNSCC cell motility." (PMID 33925575, 2021). "It has been reported that ERL inhibits epidermal growth factor receptor (EGFR) and makes tumor cells more sensitive to nucleotide damage induced by DOX." (PMID 34876140, 2021). "EGFR and ErbB2 are often over-expressed in HNC cells and are frequently prone to heterodimerization that confers tumor growth advantage." (PMID 34561494, 2021). "Here, we addressed this possibility and show for the first time the tumor targeting efficacy and anti-tumor effect of a PLGA-PEG-Cis-Pt nanosystem, equipped with a high specific EGFR aptamer (named CL4), in mice bearing TNBC xenografts." (PMID 34294133, 2021). "Hence, it is tempting to speculate that the addictive effect of EGFR overexpression for tumour growth and for tumour resistance might be less based on mitogenic signals mediated via the EGFR than survival and immune-suppressive signal driven by constitutive PLCγ signalling." (PMID 35052732, 2021). "Other exosomal molecules such as Apolipoprotein E, HSP70, Wnt4, epidermal growth factor receptor (EGFR), and integrin αVβ6 were reported to be involved in tumor progression in the recipient cells." (PMID 34677212, 2021). "Administration of BJ diminished the intensive fluorescent EGFR and phosphorylated EGFRY1068 in tumor dissections, as indicated by antibody detection." (PMID 35582384, 2021). "The oncogenes EGFR and PDGFRA are often overexpressed in primary GBs and stimulate tumor proliferation." (PMID 34210109, 2021). "The tumor expression levels of receptor tyrosine kinase genes, including VEGFR-1, VEGFR-2, PDGFR-α, PDGFR-β, ALK, EGFR, ErbB2, and B-RAF, were analyzed." (PMID 33764261, 2021). "The continuation of EGFR-TKI after local progression with concurrent radiotherapy also demonstrated better ORR and local tumor control rate, warranting further studies." (PMID 34638411, 2021). "The epidermal growth factor receptor (EGFR) is a member of the receptor tyrosine kinases (RTK) family, participating in cell proliferation, differentiation and tumor progression." (PMID 34425750, 2021). "The H&E staining and 11 IHC markers (Ki67, P63, GATA3, KRT5/6, KRT20, E-cadherin, 34βE12, PD-L1, EGFR, Nectin4, and HER2) were used to evaluate tumor phenotype maintenance." (PMID 35432811, 2021). "Although many HNSCC are EGFR-positive, PET with [64Cu]Cu-labeled mAbs would confirm lesions as EGFR-positive and importantly predict the tumour and normal tissue uptake of [177Lu]Lu-labeled anti-EGFR mAbs." (PMID 34383182, 2021). "AMPK activation, mTORC1 inhibition and EGFR-PDGFRα degradation as well as Akt inhibition and autophagy induction were detected in ASP4132-treated NSCLC xenograft tumor tissues." (PMID 33824293, 2021). "EGFR is a member of the ErbB family and can bind to ECM components such as matrikines to promote tumor cell expansion." (PMID 34178945, 2021). "Taken together, our findings demonstrate that DCN acts as a tumor- and metastasis suppressor in IBC by accelerating the autophagic degradation of E-cadherin and suppressing activation of EGFR–ERK signaling." (PMID 33452400, 2021).
tumor (continued). "Meanwhile, the phosphorylation levels of EGFR and ERK in tumor tissues of the NCI-H1975 xenograft model were analyzed by immunohistochemistry." (PMID 33986687, 2021). "Epidermal growth factor receptor (EGFR) tyrosine kinase (TK), a receptor tyrosine kinase, plays an important role in the process of survival, proliferation, angiogenesis, tumour micro environment, and adhesion of several malignant tumors." (PMID 34074193, 2021). "Numerous downstream effectors of EGFR signaling bypassing activated KRAS and promoting tumor progression have been identified, including NFATc1 and c-MYC." (PMID 34070180, 2021). "The epidermal growth factor receptor (EGFR) is a major activator of various signaling pathways and physiological responses, including migration, proliferation, survival, and tumor formation." (PMID 34210107, 2021). "EGF binds with EGFR, thus activating the epidermal growth factor receptor, activating PI3K/Akt pathway, and finally promoting tumor proliferation." (PMID 33688358, 2021). "The difference in expression comparing tumor and normal tissues were found to be significant in eight genes (PLAU, EGR1, IL6, EGFR, EZH2, BMP4, CCNB1, NMI)." (PMID 34077304, 2021). "Mechanistically, DCN functioned as a suppressor of invasion and tumor growth in IBC by destabilizing E-cadherin and inhibiting EGFR/ERK signaling." (PMID 33452400, 2021). "We evaluated the cluster formation efficiency of sorted PDX tumor cells with different CD44 and EGFR expression." (PMID 33995681, 2021). "The EGFR is a transmembrane receptor tyrosine kinase (RTK) that is critical for normal cellular function and is significantly upregulated in malignant tumor cells." (PMID 34635007, 2021). "In addition, anti-EGFR-TKIs mediate cell death via the intrinsic pathway of apoptosis, therefore high levels of mitochondrial cholesterol in tumor cells may be able to protect against cell death through changes in the permeability of the mitochondrial membrane itself." (PMID 34069851, 2021). "The relative expression of EGFR and HER2 have also been examined in 21-paired primary tumours and their metastatic sites by immunohistochemistry." (PMID 33562755, 2021). "IHC revealed that the tumor tissue grown from sh-AL355338 cells displayed lower Ki-67, ENO1, and EGFR staining than those formed from sh-NC cells." (PMID 34627260, 2021). "More recent studies have further elucidated the prominent examples of EGFR, HER2, and AXL signaling contributing directly to tumor-driven immunosuppression." (PMID 33807608, 2021). "In EGFR-TKI-resistant xenograft models, the combined administration of a SIRT1 inhibitor, tenovin-6 (Tv6), with gefitinib promoted tumor regression." (PMID 34381712, 2021). "Here, we describe a new signaling axis, involving EGFR, miR‐9, KLF5, and Sp1, that connects the tumor stem‐like features of HNSCC with the response to therapy." (PMID 34062049, 2021). "According to the tumor grades, in the TCGA database, compared with WHO II & III, the EGFR transcription level was the highest in WHO IV." (PMID 33892666, 2021). "The anti-tumor effect of VTX-2337 was determined in SCCVII/C3H, mEERL/C57Bl/6 and TUBO-human EGFR/BALB/c syngeneic mouse models." (PMID 33452311, 2021). "In this investigation, we developed a novel bispecific antibody (BsAb) targeting EGFR and VEGFR2 (designated as anti-EGFR/VEGFR2 BsAb) and investigate its anti-tumor activity using TNBC cellular and xenograft mouse models." (PMID 33804477, 2021). "Both EGFR and VEGFR2 frequently overexpress in TNBC and cooperate with each other in autocrine and paracrine manner to enhance tumor growth and angiogenesis." (PMID 33804477, 2021).